LNPK (lunapark, ER junction formation factor)
Description:
Endoplasmic reticulum (ER)-shaping membrane protein that plays a role in determining ER morphology. Involved in the stabilization of nascent three-way ER tubular junctions within the ER network. May also play a role as a curvature-stabilizing protein within the three-way ER tubular junction network. May be involved in limb development (By similarity). Is involved in central nervous system development.
Synonyms: KIAA1715; LNP; Ul; LNP1; NEDEHCC; ulnaless
Tractability: Antibody: UniProt predicts a signal peptide or a membrane-spanning region. PROTAC: ubiquitination databases record sites on it.
Gene: Protein-coding gene on chromosome 2 (175,923,882 to 176,002,839, reverse strand). Ensembl gene ENSG00000144320.
Subcellular location: Endoplasmic reticulum membrane
Subcellular location (Human Protein Atlas): Endoplasmic reticulum; Connecting piece; End piece; Mid piece; Nucleoplasm; Principal piece
Gene Ontology:
Molecular function: identical protein binding; protein binding
Biological process: endoplasmic reticulum organization; endoplasmic reticulum tubular network maintenance; positive regulation of endoplasmic reticulum tubular network organization; endoplasmic reticulum tubular network organization; limb development
Cellular component: endoplasmic reticulum; endoplasmic reticulum membrane; endoplasmic reticulum tubular network membrane; endoplasmic reticulum tubular network; membrane
Genetic constraint (gnomAD): Loss-of-function variants: 13 observed, 21.44 expected, observed/expected ratio (o/e) 0.61, 90% interval 0.39 to 0.96. The upper end of that interval is the gene's LOEUF score, 0.96, which puts it in group 4 of 6, group 1 being the genes least tolerant of losing a copy. Missense variants: 285 observed, 292.53 expected, observed/expected ratio (o/e) 0.97, 90% interval 0.88 to 1.08. Synonymous variants: 95 observed, 103.29 expected, observed/expected ratio (o/e) 0.92, 90% interval 0.78 to 1.09.
Homologues: Orthologues: chimpanzee LNPK (99% identical), macaque LNPK (97% identical), dog LNPK (90% identical), rabbit LNPK (89% identical), pig LNPK (86% identical), mouse Lnpk (85% identical), rat Lnpk (83% identical), guinea pig LNPK (70% identical), tropical clawed frog lnpk (57% identical), zebrafish lnpk (52% identical), zebrafish lnpa (29% identical), Drosophila melanogaster Lnpk (28% identical), and 1 more.
Diseases named in the same sentence as LNPK in open-access papers:
LNPK is named in the same sentence as 12 diseases in open-access papers, as found by Europe PMC text mining. Sharing a sentence is not in itself a finding about the gene and the disease. The quoted sentences say what the papers report.
epilepsy (4 papers, 2019 to 2024). A brain disorder characterized by episodes of abnormally increased neuronal discharge resulting in transient episodes of sensory or motor neurological dysfunction, or psychic dysfunction. "All affected individuals of our and previous cohorts harbour LoF homozygous variants in LNPK, resulting in a neurodevelopmental phenotype characterized by moderate to profound DD/ID, refractory epilepsy and a recognizable neuroradiological pattern." (PMID 37794925, 2023). "Recently, homozygous variants in LNPK were shown to cause a neurodevelopmental disorder (OMIM#618090) in four patients displaying developmental delay, epilepsy and nonspecific brain malformations including corpus callosum hypoplasia and variable impairment of cerebellum." (PMID 37794925, 2023).
Parkinsonism (1 paper, 2023). Characteristic neurologic anomaly resulting from degeneration of dopamine-generating cells in the substantia nigra, a region of the midbrain, characterized clinically by shaking, rigidity, slowness of movement and difficulty with walking and gait. "Neurological follow-up of affected individuals with LNPK pathogenic variants will be important to determine whether they may develop parkinsonism later in life like in the ATP13A2-related disorders, which could be potentially treated." (PMID 37794925, 2023).
rheumatoid arthritis (1 paper, 2023). A chronic, systemic autoimmune disorder characterized by inflammation in the synovial membranes and articular surfaces. "Notably, cg26878734 (LNPK) was previously associated with rheumatoid arthritis in a monozygotic twin study, suggesting its involvement in inflammation, while genetic variability at the CCDC178 gene has been associated with body fat distribution in a genome-wide association study." (PMID 37393279, 2023).
LNPK also shares sentences with these, for which no sentence is quoted: Intellectual disability (2 papers); neurodevelopmental disorder (2); brain malformations (1); developmental delay (1); Dystonia (1); hereditary spastic paraplegia (1); infection (1); neurodegenerative disease (1); tumor (1).